Y_RNA (Y RNA )
Gene: Miscellaneous RNA gene on chromosome 4 (157,768,013 to 157,768,113, reverse strand). Ensembl gene ENSG00000200521.
Homologues: Orthologues: chimpanzee Y_RNA (100% identical), macaque Y_RNA (96% identical), guinea pig Y_RNA (93% identical). Paralogues in human: RNY3 (96% identical), Y_RNA (96% identical), RNY3P1 (95% identical), Y_RNA (95% identical), Y_RNA (94% identical), Y_RNA (93% identical), RNY3P11 (92% identical), Y_RNA (92% identical), Y_RNA (91% identical), Y_RNA (90% identical), RNY3P14 (89% identical), Y_RNA (89% identical), and 99 more.